ASAH1 (N-acylsphingosine amidohydrolase 1)
Diseases named in the same sentence as ASAH1 in open-access papers (continued):
Sharing a sentence is not in itself a finding about the gene and the disease.
tumor (continued). "In our study, MCL inhibited the activation of pAKT/ASAH1 by reducing ROS accumulation in ER‐positive BC cells, especially TAMR cells, thereby suppressing tumour proliferation." (PMID 38924190, 2024). "ASAH1 further promotes the nuclear export of PTEN via the downstream product S1P, thereby promoting cell proliferation and tumour therapeutic resistance." (PMID 38924190, 2024). "In summary, these results provided evidence that combined treatment with the ASAH1 inhibitor carmofur and the MAPK pathway inhibitor trametinib can lead to significant inhibition of TNBC tumor growth." (PMID 38926346, 2024). "Our data support the concept that the selectively increased expression of DEGS1 and ASAH1 in TSC tumor cells leads to increased sphingolipid biosynthesis, which in turn enhances TSC tumor cell viability and growth in preclinical models." (PMID 36927688, 2023). "The mRNA levels of ceramidase (ASAH1), S1P precursor enzyme, and STING were inversely correlated in healthy lung tissues, but positively correlated in tumor tissues." (PMID 37176007, 2023). "Receiver operating characteristic curve analysis revealed a modest capacity for ASAH1 expression to differentiate between tumor and non-tumor tissue in LARC patients (AUC=0.652, p=0.042)." (PMID 41313810, 2025). "Based on our results that ASAH1 regulates MAPK pathway, we investigated whether the MAPK pathway inhibitor trametinib, an MEK inhibitor, can exert a tumor-suppressive effect in TNBC cells, similar to that observed for the ASAH1 inhibitor carmofur." (PMID 38926346, 2024). "Importantly, TCGA heatmap analysis suggests that ASAH1 is the only ceramidase that is expressed highly in the GBM tumor, as compared to non-tumor brain." (PMID 35741006, 2022). "Data mining of our previous human HCC transcriptome dataset showed that the gene expression of CERS2, CERS4, CERS5, and CERS6 was significantly increased in HCC tumors compared with that in non-tumor adjacent tissues, while no obvious difference was observed in ASAH1 gene expression." (PMID 33803928, 2021). "In contrast, the gene expression of CERS4 and CERS5, but not ASAH1, was significantly increased in HCC tumors than that in non-tumor adjacent tissues." (PMID 33803928, 2021). "In addition, in healthy, non-tumor samples, STING and ASAH1 were not correlated to each other." (PMID 37176007, 2023).
infection (13 papers, 2014 to 2025). The state of being infected such as from the introduction of a foreign agent such as serum, vaccine, antigenic substance or organism. "Our qRT-PCR data revealed that sphingolipid metabolic key genes encoding enzymes: Cers2, Gba2, Gla, Asah1, Asah2, Acer2, Acer3, Neu3, Sgpp1, and Sphk1 were robustly upregulated in mRNA levels by the infection of C. sinensis." (PMID 36339341, 2022). "The result showed that during ALV-J infection, the levels of ASAH1, NAAA, CHKA, PGS1, SGPP1, DEGS2, and SMPD1 genes were significantly increased with infection time." (PMID 38598912, 2024). "We concluded that Asah1 is not induced during infection or by IFN-I, however IRF8 regulates Asah1 expression during development of macrophages." (PMID 32165633, 2020). "Similarly, we did not observe changes in the expression of the lysosomal enzymes ASAH1 and SMPD1 which could account for the increased Cer and/or Sph levels upon infection." (PMID 40249190, 2025). "Therefore we concluded that Asah1 is not specifically upregulated during infection, but shows already basal activity in macrophages before infection." (PMID 32165633, 2020).
metabolic disease (6 papers, 2017 to 2024). A congenital disorder (due to inherited enzyme abnormality) or acquired (due to failure of a metabolically important organ) disorder resulting from an abnormal metabolic process. "Genetic variations of ASAH1 have been associated with exercise tolerance and skeletal/cardiac muscle adaptation to exercise, which can condition adherence to physical activity regimens necessary for a healthy lifestyle, thereby increasing the individual risk of metabolic diseases." (PMID 32498325, 2020).
neurodegenerative disease (4 papers, 2018 to 2025). A disorder of the central nervous system characterized by gradual and progressive loss of neural tissue and neurologic function. "Of these APOE, APOC1 and ASAH1 are involved in lipid metabolism and neurodegenerative diseases." (PMID 35388616, 2022). "This study revealed that the five biomarkers, GLB1, ARSB, ASAH1, HEXB, and PSAP are all enriched in the lysosomal, chemokine, oxidative phosphorylation, and neurodegenerative disease pathways." (PMID 40534738, 2025).
adenocarcinoma (2 papers, 2018 to 2023). A common cancer characterized by the presence of malignant glandular cells. "Inhibiting ASAH1 activity resulted in the accumulation of intracellular ceramide up to cytotoxic levels, that induced a significant amount of apoptosis in SW403 human adenocarcinoma cells when exposed to the ASAH1 inhibitor B13." (PMID 29642535, 2018). "ASAH1+STING+ patients had a lower survival rate than ASAH1-STING+ adenocarcinoma patients." (PMID 37176007, 2023).
neurological disease (2 papers, 2024 to 2025). "Notably, many of these DEGs have been associated previously with neurological disease including SPHK2 (sphingosine kinase 2); P2RX7 (purinergic receptor P2X 7); SMPD4 (sphingomyelin phosphodiesterase 4); ASAH1 (N-acylsphingosine amidohydrolase 1)." (PMID 38625017, 2024).
renal disease (1 paper, 2025). "ASAH1 is a major regulator of Cer–Sph balance, and its dysregulation has been shown to drive Cer accumulation, promoting apoptosis and fibrosis in renal disease contexts." (PMID 41226412, 2025).
vasculopathy (1 paper, 2023). "These smooth muscle-specific Asah1 gene knockout mice were used to study the high mobility group box 1 (HMGB1) signaling axis in ACDase-deficiency-mediated vasculopathy." (PMID 36830643, 2023).
ASAH1 also shares sentences with these, for which no sentence is quoted: Gaucher disease (6 papers); hepatoma (5); leukemia (5); liver fibrosis (5); bacterial infections (4); Fabry disease (4); Hepatic steatosis (4); Atopic Dermatitis (3); colitis (3); COVID-19 (3); genetic disorder (3); Lipid storage disease (3); myocardial infarction (3); ovarian carcinoma (3); Arthritis (2); depression (2); epilepsy (2); hemangiosarcoma (2); juvenile idiopathic arthritis (2); membranous nephropathy (2); metachromatic leukodystrophy (2); minimal change disease (2); neuronal ceroid lipofuscinosis (2); Niemann-Pick disease (2); non-Hodgkin lymphoma (2); osteosarcoma (2); rectal cancer (2); synucleinopathies (2); ulcerative colitis (2); Viral infections (2).
A further 67 diseases each share a sentence with ASAH1 in 1 paper.